RN7SL547P (RNA, 7SL, cytoplasmic 547, pseudogene)
Gene: Miscellaneous RNA gene on chromosome 20 (7,633,562 to 7,633,851, reverse strand). Ensembl gene ENSG00000240584.
Homologues: Orthologues: chimpanzee Metazoa_SRP (99% identical), macaque Metazoa_SRP (89% identical). Paralogues in human: RN7SL1 (77% identical), RN7SL2 (77% identical), RN7SL3 (77% identical), RN7SL126P (75% identical), RN7SL451P (75% identical), RN7SL481P (75% identical), RN7SL664P (75% identical), RN7SL851P (75% identical), RN7SL612P (74% identical), RN7SL621P (74% identical), RN7SL743P (74% identical), RN7SL177P (74% identical), and 703 more.